TNF (tumor necrosis factor)
Diseases named in the same sentence as TNF in open-access papers (continued):
Sharing a sentence is not in itself a finding about the gene and the disease.
COVID-19 (continued). "The combined application of these cell death stimuli mirrored the COVID-19 cytokine storm, and the application of TNF-alpha- and IFN-gamma-neutralizing antibodies protected against SARS-CoV-2 in mice." (PMID 35997950, 2022). "High serum IL-6 and TNF-α levels are two strong and independent survival predictors of patient with COVID-19." (PMID 35356515, 2022). "Supernatants were subsequently analyzed for key inflammatory cytokines associated with the cytokine storm in COVID-19 (IFN-γ, IL-1β, IL-2, IL-4, IL-6, IL-8, IL-10, IL-12p70, IL-13, and TNF-α), using the Meso Scale platform." (PMID 36296272, 2022). "Among the inflammatory mediators released by immune cells, the cytokines IFN-α, IFN-γ, IL-1β, IL-6, IL-12, IL-18, IL-33, TNF-α and TGF-β are highlighted, and altered levels are associated with different clinical features of COVID-19." (PMID 35846757, 2022). "Patients on anti-tumor necrosis factor (TNF) or ustekinumab should discontinue treatment if they develop COVID-19." (PMID 35464519, 2022). "Case studies have suggested that patients on anti-TNF therapy for rheumatic diseases tend to have lower hospitalization rates from COVID-19, suggesting a prophylactic effect of anti-TNF therapy in the disease pathogenesis." (PMID 36419185, 2022). "It has been shown that both in MAS and HLH, but especially in severe COVID-19, it is implicated the dysfunction of type I interferon, NK cells, with extensive CTL involvement, increased IL-6, TNF-α, and excessive inflammation caused by the NF-kB pathway." (PMID 35457086, 2022). "Particular attention must be paid to the inhibition of factors such as IL6, GCSF, GMCSF, and TNFα that are associated with highly severe disease and ICU admission of COVID-19 patients." (PMID 36140223, 2022). "Clinical trials are urgently needed to test different TNF-α/NF-κB inhibitors or HMGB1 antibodies for treatment or prevention of severe COVID-19 cases." (PMID 35992691, 2022). "Patients with COVID-19 had significantly higher CSF concentrations of neopterin, β2M, interleukin (IL) 2, IL-6, IL-10, and tumor necrosis factor α (TNF-α) compared with controls." (PMID 35604688, 2022). "A study of a longitudinal serum cytokine analysis of 207 COVID-19 patients showed that in very early inflammatory responses, IL-6, TNF-a, IL-10, and IL-1b rose in those with more severe disease." (PMID 35223745, 2022). "In the present study, subjects in the post-COVID-19 group had higher levels of IL-17, TNF-α and IL-2 as compared to the acute COVID-19 group." (PMID 35846757, 2022). "For example, the study by Del Valle el al. is consistent with our results, which reported the higher levels of IL-6 and TNF-α in COVID-19 male patients than healthy subjects." (PMID 36381078, 2022). "The hyperinflammatory status which occurs in a cytokine storm is caused by the release of numerous proinflammatory cytokines, such as IL-6, IL-1, TNF-alpha, etc., with IL-6 as the orchestral lead for COVID-19 cytokine release syndrome." (PMID 35629072, 2022). "We began by examining serum levels of IL-1β, IL-6, IL-10 and TNFα at ICU admission in all serum samples from our Cytokine Cohort of 90 COVID-19 patients." (PMID 36451808, 2022). "Controversially, another study indicated that in severe COVID-19 cases, peripheral blood monocytes significantly increased expression of IL-6, TNF, IL-1β, and their receptors, as well as pro-inflammatory chemokines including CCL2, CCL3, and CCL4." (PMID 35632823, 2022). "The inflammation of the olfactory epithelium in COVID-19 seems to be supported by the release of cytokines such as IL-1, IL-6, IL-12, IL-15, and TNF-α, and by activating lymphocytes and macrophages, initiating the so-called “cytokine storm”." (PMID 35269410, 2022). "As increased serum levels of TNF alpha have been detected in many patients with severe COVID-19 compared to subjects with mild disease, the use of TNF-α inhibitors was proposed at the beginning of the outbreak with therapeutic purpose against COVID-19." (PMID 35566548, 2022).
COVID-19 (continued). "Increased levels of β-glucan were seen in COVID-19 patients who also exhibited higher levels of TNF-α, IL-1β, IL-6, IL-8, and LPS." (PMID 36297092, 2022). "As far as TNFα inhibitors exclusively meant for an anti-COVID-19 treatment are concerned, a clinical trial evaluating adalimumab has been reported in China (ChiCTR2000030089)." (PMID 36289890, 2022). "In COVID-19 patients, the studies reported elevated interleukins (IL) like IL-6, IL-8, IL-2R, IL-10, tumor necrosis factor (TNF-α), IL-1Ra, IP-10 (IFN-γ-induced protein 10) and macrophage inflammatory protein 1 (MCP-1), especially in the severe group." (PMID 35109926, 2022). "Our results evidence that patients with COVID-19 residing in high-altitude tend to have higher levels of inflammatory cytokines, particularly IL-6, IL-10 and TNF-α." (PMID 35090394, 2022). "Taken together, the favorable outcome observed in IBD patients treated with anti TNFs support a potentially protective effect of TNF inhibition in COVID-19, but further investigations are required." (PMID 35335008, 2022). "Apart from its role in COVID-19, TNF-α plays a major role in several chronic inflammatory diseases and immunosuppressive therapies targeting TNF-α have proved beneficial in these conditions." (PMID 36056419, 2022). "In severe COVID-19, the major cytokines generated as part of immune response are IL-1β, IL-2, IL-6, and TNF." (PMID 35281470, 2022). "This further increases IL-1, IL-6, and TNF-α secretions, and it contributes to COVID-19 post-infective acute myocarditis." (PMID 35464491, 2022). "Particularly, previous studies identified a strong association of the COVID-19 severity with IFN type I and TNF alpha responses." (PMID 36230912, 2022). "Increased plasma levels of pro-inflammatory cytokines and chemokines (especially IL-2, IL-6, IL-10, and TNF-α) with impaired IFN-I activation in severe COVID-19." (PMID 36072602, 2022). "For instance, elevated levels of interleukin (IL)-6, IL-1, TGF-β, and TNF-α have been detected in COVID-19 patients." (PMID 35016612, 2022). "The use of vitamin E combined with vitamins A, C, B, and D, reduced ESR, CRP, IL-6, TNF-a, and hospitalization time in adults with COVID-19." (PMID 36295088, 2022). "In summary, antiviral T cells reactive against PepTivator SARS-CoV-2 Select were detectable in convalescent COVID-19 patients and these were mainly TNF-α and IFN-γ producing CD8+ and CD4+ T cells." (PMID 35480981, 2022). "Expression level of TNF-α was significantly lower both in recovered COVID-19 patients and vaccinated women in comparison to healthy controls." (PMID 35283772, 2022). "Adalimumab, a humanized anti-TNF-α monoclonal antibody, has been utilized with remdesivir and dexamethasone for severe COVID-19 patients in a randomized controlled trial." (PMID 35697684, 2022). "Research found that plasma concentrations of IL-2, IL-7, IL-10, and tumor necrosis factor- α (TNF-α) of COVID-19 patients admitted to the ICU were higher than those of non-ICU patients." (PMID 36341356, 2022). "Andrographolide can bind to TNF and NFkB1 proteins to block the NFkB1 signaling pathway of TNF-induced cytokine storm in COVID-19 patients." (PMID 36238575, 2022). "TNF-α expression, on the other hand, differed between the two COVID-19 groups insignificantly (P = 0.13)." (PMID 35982898, 2022). "Recently, in a coronavirus disease 2019 (COVID-19) study, PTL served as a herbal candidate for COVID-19 clinical evaluation by reducing cytokines, including IL-1, IL-2, IL-8, and TNF-α, and inhibiting inflammatory signaling pathways." (PMID 35514960, 2022). "The role of cytokines in the physiopathology of COVID-19 has been widely documented, and the circulant levels of cytokines such as Il-6 and TNF-alpha are strong predictors of COVID-19 progression." (PMID 36012503, 2022). "COVID-19 patients showed an impaired T cells characterized with lower T cell proliferation and T cells with lower expression of TNFα and INFγ." (PMID 36369012, 2022).
COVID-19 (continued). "Recent data have indicated that patients with COVID-19 also had high concentrations of serum cytokine profiles, such as TNF-α, IL-1, IL-6, and IFN-γ." (PMID 35346253, 2022). "In COVID-19 patients, excessive release of cytokine, including IL1-β, IL-2, IL-6, IL-7, IL-8, IP10, MCP1, MIP1A, and tumor necrosis factor-α (TNF-α), exacerbated COVID-19 manifestation." (PMID 36203683, 2022). "Among these, we observed a significant decrease in the three best documented general pro-inflammatory markers in COVID-19: IL-6, IL-1β and TNF-α." (PMID 36466830, 2022). "The IL-6 antagonist and TNF-α inhibitor are likely to be a proper therapeutic strategy to reduce mortality in males with COVID-19 and in Western countries." (PMID 35237162, 2022). "This study shows that survivors of COVID-19 have reduced brachial artery FMD that is inversely correlated with concentration of TNF-α after 327 days from diagnosis." (PMID 35237624, 2022). "After the diagnosis of COVID-19, 52% (30/58) and 36% (27/75) of patients taking thiopurines and anti-TNFα antibodies, respectively, discontinued the medication." (PMID 35089397, 2022). "IL-1β can enhance inflammatory responses in the bronchi and alveoli in patients with lung injury, and the levels of inflammatory cytokines such as IL-1 and TNF are elevated in the lungs of patients with COVID-19." (PMID 35464491, 2022). "Since blocking IL-6 met with limited success in COVID-19 patients, anti-TNF therapy has been recently considered as a means of reducing inflammation in COVID-19." (PMID 34983527, 2022). "We believe the large number of purUUpurU in SARS-CoV-2 contributes to the markedly elevated levels of proinflammatory cytokines including IL-1, TNF, and interleukin 6 (IL-6) in severe COVID-19." (PMID 36420234, 2022). "If new indications of TNF and IL-17 inhibitors can be found, the time period of drug development will be greatly shortened and the success rate of drug discovery for COVID-19 will be improved." (PMID 35935817, 2022). "TNF-α was significantly higher in severe COVID-19 patients than healthy subjects (12.0 ± 0.9 vs 6.9 ± 0.3 pg/mL, p = 0.003, t-test)." (PMID 35508575, 2022). "We found patients with pulmonary PASC had significantly elevated frequencies of IFN-γ- and TNF-α-producing SARS-CoV-2-specific T cells compared to participants with resolved COVID-19 (RC)." (PMID 35617421, 2022). "AAT acts as an inhibitor of inflammatory molecules (e.g., IL-8, TNF-α) and of proteases involved in the pathophysiology of COVID-19 (e.g., elastase, TMPRSS2 and ADAM17)." (PMID 35163482, 2022). "For example, procoagulant endothelial EVs are released due to endothelial damage, TNF-α, or complement activation resulting in coagulation and venous thromboembolism, presented in COVID-19, as deep vein thrombosis or pulmonary embolism." (PMID 36268783, 2022). "In contrast, G-CSF, IL-1RA, IL-17a, IL-1b, INFγ, MCP3 and TNFα were undetectable or negligible in the serum and CSF of both the HC and the COVID-19 group." (PMID 35479062, 2022). "Levels of IL-6 and TNF-α in the serum can be considered for the COVID-19 patient treatment and management for the clinical trials, to guide resource allocation and therapeutic options." (PMID 36078094, 2022). "This study attempts to explore and evaluate the correlation between the severity of COVID-19 and different contributors such as testosterone and inhibin B as sex-related parameters and the inflammatory mediators; IL-6 and TNF-a among Jordanian males." (PMID 36381078, 2022). "Among the PICs, TNF-α and IFN-γ promote inflammatory cell death leading to a cytokine storm, which is a major cause of COVID-19-associated mortality." (PMID 36230930, 2022). "In the case of TNF-α, a clear tendency can be observed, with more healthy subjects from Lima showing values in the lower quartiles, while most of the healthy and COVID-19 patients from Huaraz are categorized in the upper ranges." (PMID 35090394, 2022).
COVID-19 (continued). "The results show that MMP-7, TGF-β, IL-10, IL-7, TNF-α, and IL-6 were significantly correlated with high lung involvement in COVID-19 patients." (PMID 36286038, 2022). "The co-administration of TNF and IFN-γ in mice causes lethal shock, with physiological symptoms that are consistent with those seen in patients with severe COVID-19, including multiorgan damage and dysfunction." (PMID 36419185, 2022). "Hypertensive disorders of pregnancy and COVID-19 share an exaggerated inflammatory response, guided by cytokines such as IL-6, TNF-α and IFN-γ leading to endothelial damage." (PMID 36471262, 2022). "Data on anti-TNFα effects in COVID-19 patients are limited, although current treatment guidelines advise against the use of anti-TNFα in patients with acute COVID-19 infection." (PMID 35089243, 2022). "Levels were most pronounced in samples taken at early time points post onset of COVID-19 symptoms with the exception of TNF-α and IL-18 which remained high in all hospitalised patients or even increased (IL-18) in samples taken at day 21-30 post symptoms." (PMID 36275702, 2022). "Accordingly, previous reports state that the COVID-19 patients, who have been on anti-TNFα therapy, show lesser disease severity and fewer hospitalization cases." (PMID 36574379, 2022). "An additional study observed higher TNFα and IP-10 in the early recovery phase from primary COVID-19 in adults who would go on to experience PASC." (PMID 36032119, 2022). "This is significant because TLR7/8 activation of NF-κB increases cytokine production and, in conjunction with inflammasome activity, NF-κB drives an axis of IL-1β, IL-6, IL-12, TNFα, and Th1 T-cell hyperinflammation as part of COVID-19 immunopathology." (PMID 35261923, 2022). "As with TNF alpha, mean serum levels of IL-17 in patients with COVID-19 have also been shown to be substantially higher than values detected in the general population." (PMID 35566548, 2022). "In light of this, we review the efficacy of specific inhibitors of IL6, IL1, IL-17, and TNF-α for treating COVID-19-related infections to manage COVID-19 and improve the survival rate for patients suffering from severe conditions." (PMID 35619180, 2022). "The mean TNF-α levels were found to be significantly higher in COVID-19 patients who died compared with COVID-19 survivors." (PMID 35215138, 2022). "Reports of IFN-γ and TNFα sensitizing the cells to initiate inflammatory cell death in lung cells have been documented in COVID-19." (PMID 36415655, 2022). "When stimulated with cytokines IL-12 and IL-18, impaired upregulation of IL-17A, TNFα, granzyme B and perforin was observed in the COVID-19 cohort, and a reduction in perforin was observed." (PMID 34050887, 2022). "NLRP3 assembly with consequent activation of caspase-1 and downstream consequences like increased active TNF-alpha, IL-1beta and IL-18 are increased in the lungs of fatal COVID-19 cases." (PMID 36555204, 2022). "Interestingly, TNF-α induced apoptosis of lymphocytes was shown to increase with age, and may potentially link extrinsic apoptosis with the increased risk of severe COVID-19 in older people." (PMID 35244141, 2022). "High levels of cytokines, such as IL-6, IL-1β, TNF-α, and IFN-γ, have been detected in COVID-19 patients, causing a syndrome called cytokine storm, which is believed to be the main cause of tissue damage in the pathophysiology of COVID-19." (PMID 35062298, 2022). "Another suggestion seems to be that in COVID-19 cases, elevated pro-inflammatory cytokine levels such as tumor necrosis factor (TNF) and IL-6 promote the apoptosis of lymphocytes." (PMID 36277580, 2022). "BALF-derived macrophages from patients with COVID-19 show especially high response scores for IL-1β and TNF in their pro-inflammatory subset." (PMID 35732153, 2022). "Reports show that an overactive TNF signaling pathway has been identified as a key contributor to the development and severity of COVID-19." (PMID 35992697, 2022).
COVID-19 (continued). "The exception to this was TNF-α, where the highest tertile of mild COVID-19 patients had an increase in NfL similar to the severe COVID-19 groups." (PMID 35938070, 2022). "We conducted a systematic review followed by meta-analysis including studies covering genetic association of COVID-19 susceptibility or prognosis with IFITM3, FURIN, ACE1, and TNF-α variants." (PMID 35432458, 2022). "IL-2R, IL-6, IL-10 and TNF-α, which were correlated with gender or regions of COVID-19 patients, were finally presented in this study." (PMID 35237162, 2022). "We identified three key pathways (pathways in cancer, the TNF signaling pathway, and lipid and atherosclerosis) involved in the treatment of COVID-19 with active phytomolecules of Kochiae Fructus." (PMID 35992697, 2022). "These connections make the interactions of the inflammatory markers, specifically IL-6 and TNF-α with testosterone and inhibin B in COVID-19 patients an intriguing target of further exploration by immunologists, physiologists and drug researchers." (PMID 36381078, 2022). "Although ADO signaling is compromised in leukocytes of severe COVID-19 patients, we verified that in vitro treatment can attenuate the production of TNF-α and IL-6 in CMNs after activation." (PMID 36248842, 2022). "COVID-19 convalescents were found to have increased concentrations of IL-17 and counts of TNFα-producing CD4+ T helpers, while both the TNFα+ and IFNγ+ cell percentages were increased among cytotoxic T cells." (PMID 35337053, 2022). "Pro-inflammatory cytokines, such as TNF-α, are the target of a potential therapeutic strategy in the treatment of severe and critical cases of COVID-19 patients." (PMID 36579506, 2022). "Overall, serum or plasma TNF-alpha was determined in 63 samples from 26 patients during hospitalization for COVID-19 and was elevated (median 31.8 pg/ml; percentile range [0.1–0.9] 17.65–56.48; cut-off 15) in 51 (81%) of them." (PMID 35057809, 2022). "NKG2A expression is upregulated on NK cells and CTLs in COVID-19 patients, with a decreased capacity to produce CD107a, IFN-γ, IL-2, granzyme B and TNF-α., which suggests functional exhaustion of cytotoxic lymphocytes in COVID-19 patients." (PMID 35833134, 2022). "A significant cytokine storm has been described in patients with severe COVID-19, with elevated serum levels of pro-inflammatory cytokines such as interleukin (IL) 1, IL-6, IL-10, and tumor necrosis factor (TNF)-α." (PMID 35453522, 2022). "Acute inflammation increases cytokine load, such as IL-2, IL-7, and TNF, which contribute to the cytokine storm seen in COVID-19." (PMID 35746659, 2022). "Individuals who recovered from severe disease presented almost overlapping results as those observed after stimulation with N and M. Moreover, they also displayed a higher percentage of TNF+IL-17+ within CD4+ T cells if compared to COVID-19 severe and HD." (PMID 35887351, 2022). "Multiple agents found in the plasma of COVID-19 patients, such as TNF-α and IL-8, can induce chemotaxis of MC." (PMID 36225927, 2022). "When stimulated in vitro, the monocytes from COVID-19 patients synthesized significantly lower levels of pro-inflammatory cytokines IL-1β, TNFα, IL-6, and MCP-1, compared to the cells obtained from apparently healthy donors." (PMID 35632823, 2022). "This meta-analysis aims to determine the relationship, if any, between TNF-α, IL-6, vitamin D, and COVID-19 severity and mortality." (PMID 35215138, 2022). "TNF-α is a proinflammatory cytokine released by macrophages and monocytes during acute inflammation and was found to be elevated in COVID-19 patients in general; however, more pronounced levels were detected in severe cases." (PMID 35062368, 2022). "At this time, the randomized trials still focus on immunotherapy in acute COVID-19: in contrast, our data suggests continuous upregulation of TNFα after the infection phase." (PMID 36405747, 2022).